AQP4 (aquaporin 4)
Diseases named in the same sentence as AQP4 in open-access papers (continued):
Sharing a sentence is not in itself a finding about the gene and the disease.
neuromyelitis optica spectrum disorder (continued). "Neuromyelitis optica spectrum disorder (NMOSD) is an autoimmune inflammatory disease of the central nervous system (CNS), characterized by Th17 cell responses and serum antibodies against the water channel aquaporin-4 (AQP4) on astrocytes." (PMID 41497588, 2025). "Not all cases were evaluated for AQP4-IgG, the indicator for neuromyelitis optica spectrum disorder." (PMID 40898301, 2025). "In a pediatric study, LME was observed exclusively in MOGAD cases and was absent in pediatric-onset multiple sclerosis (POMS) or aquaporin-4 antibody-positive neuromyelitis optica spectrum disorder (AQP4-NMOSD)." (PMID 41208985, 2025). "Demographic and clinical characteristics of neuromyelitis optica spectrum disorder (NMOSD) patients with aquaporin-4 immunoglobulin G (AQP4-IgG) categorized based on the presence or absence of oligoclonal bands (OCBs)." (PMID 40160821, 2025). "MOG-IgG can be detected in AQP4-IgG negative neuromyelitis optica spectrum disorder and ON, and some of these patients will develop a recurrent form of the disease." (PMID 41235231, 2025). "Multiple sclerosis and NMOSD were considered but deemed unlikely based on clinical presentation, absence of typical imaging features, and negative neuromyelitis optica/aquaporin-4 (NMO/AQP-4 IgG) antibodies." (PMID 40909059, 2025). "The diagnosis of anti-GQ1b antibody syndrome was established based on the absence of AQP4 antibody which are specific markers for neuromyelitis optica spectrum disorders and the presence of anti-GQ1b antibody." (PMID 39742267, 2024). "Serum and cerebrospinal fluid aquaporin-4 antibody testing and serum myelin oligodendrocyte glycoprotein testing were negative, effectively lowering seropositive neuromyelitis optica spectrum disorder on the list of differential diagnoses." (PMID 39720826, 2024). "This post hoc analysis of the randomized, placebo‐controlled N‐MOmentum study (NCT02200770) of inebilizumab in neuromyelitis optica spectrum disorder (NMOSD) evaluated relationships between circulating B‐cell subsets and aquaporin‐4 immunoglobulin G (AQP4‐lgG) titers and attacks." (PMID 39222408, 2024). "Neuromyelitis optica spectrum disorder (NMOSD) is an inflammatory autoimmune disease primarily mediated by Aquaporin-4 (AQP4) antibodies, that preferentially affects AQP4-riched regions such as the optic nerve, spinal cord, area postrema (AP), brainstem and diencephalon." (PMID 38773402, 2024). "Neuromyelitis optica spectrum disorder (NMOSD) is a rare and severe inflammatory autoimmune disease of the central nervous system (CNS) that was identified as a distinct clinical entity with the discovery of aquaporin-4 immunoglobulin G antibodies (AQP4-IgG)." (PMID 37676297, 2024). "In both studies patients, neuromyelitis optica patients, as defined by 2006 Wingerchuk criteria, regardless of AQP4-IgG expression or AQP4-IgG seropositive NMOSD patients with either single or recurrent events of myelitis or optic neuritis, were included." (PMID 38558672, 2024). "The impact of early intervention with immunosuppressive treatment (IST) in anti-Aquaporin4-antibody (AQP4-ab) seropositive neuromyelitis optica spectrum disorder (NMOSD) has not been thoroughly evaluated." (PMID 39555058, 2024). "A monoclonal AQP4-specific antibody called aquaporumab, has been utilized to lessen neuromyelitis optica pathology in vivo; however has not been evaluated in TBI." (PMID 38808718, 2024). "Neuromyelitis optica spectrum disorder (NMOSD) is a central nervous system inflammatory demyelinating disease, the pathogenesis of which involves autoantibodies targeting the extracellular epitopes of aquaporin-4 on astrocytes." (PMID 36771078, 2023). "The most common presentations are optic neuritis (ON), acute disseminated encephalomyelitis (ADEM), transverse myelitis, aquaporin 4 (AQP4)-IgG negative neuromyelitis optica spectrum disorders (NMOSD), brainstem syndrome, and cortical encephalitis." (PMID 36729854, 2023).
neuromyelitis optica spectrum disorder (continued). "We report on a patient with MFS that was positive for GQ1b and aquaporin-4 antibodies but negative for myelin oligodendrocyte glycoprotein antibodies and is devoid of any features of neuromyelitis optica spectrum disorder." (PMID 37581199, 2023). "Subsequent studies showed that MOG antibodies were also present in patients with optic neuritis, myelitis, neuromyelitis optica spectrum disorder (NMOSD) phenotype without aquaporin 4 (AQP4) antibodies, and brainstem and cerebral cortical encephalitis." (PMID 37789888, 2023). "Although DENV infection of astrocytes has not been confirmed, AQP4 antibodies affecting AQP4 localization and function in astrocytes exposes this cell type as a possible contributor to the neurologic symptoms of neuromyelitis optica spectrum disorder." (PMID 36834929, 2023). "The application of cell-based assays (CBA) has clarified MOGAD diagnoses for patients who were previously categorized as anti–aquaporin-4 immunoglobulin G (AQP4-IgG)-negative neuromyelitis optica spectrum disorders (NMOSD)." (PMID 38259484, 2023). "Formerly known as neuromyelitis optica, NMOSD was considered a subtype of multiple sclerosis (MS) until 2004 when a specific serum antibody, shown to target extracellular conformational epitopes of the water channel protein aquaporin-4 (AQP4), was detected." (PMID 36771078, 2023). "Despite rigorous confirmation with reliable assays, some individuals showing the neuromyelitis optica spectrum disorder (NMOSD) phenotype remain negative for both aquaporin-4 (AQP4) and myelin oligodendrocyte glycoprotein (MOG) antibodies." (PMID 35413922, 2022). "Neuromyelitis optica spectrum disorder (NMOSD) is an autoimmune disease of the central nervous system that repeatedly involves the optic nerve and spinal cord and is mediated by aquaporin-4 (AQP4) antibodies." (PMID 35126400, 2022). "Different from neuromyelitis optica having the sensitive and highly specific serum marker (Antibodies to aquaporin-4, AQP4-Ab), the lack of effective biomarkers is an issue of MS diagnosis and treatment." (PMID 35571066, 2022). "MOG-antibody disease patients resemble clinically the neuromyelitis optica spectrum disorders in the predilection for relapses of optic neuritis and transverse myelitis and do not have aquaporin 4 (AQP4) autoantibodies." (PMID 34149706, 2021). "This was because the existence of AQP4‐IgG in some patients with neuromyelitis optica was not yet known at the time of their injury." (PMID 33591639, 2021). "Type-I IFN contributes to the disease progression, as loss of aquaporin-4 and GFAP following intracerebral injection of IgG from a neuromyelitis optica patient was alleviated in mice lacking IFNAR." (PMID 34804074, 2021). "With further understanding of clinical, radiological, and immunological characteristics of neuromyelitis optica spectrum disorder (NMOSD), especially aquaporin‐4 (AQP4) antibody, NMOSD as an independent central nervous system disease has attracted more and more attention." (PMID 34520629, 2021). "Discussion: an atypical optic neuritis may indicate a neuromyelitis optica spectrum disorder (NMOSD), which should be further characterized by determination of Aquaporin 4(AQP4)-IgG and MOG-IgG." (PMID 32705325, 2021). "The presence of MOG-Ab identifies a subset of adults and children meeting the clinical and imaging criteria for neuromyelitis optica spectrum disorder (NMOSD) without antibodies to aquaporin-4." (PMID 30671648, 2019). "Features suggestive of MOG-IgG as opposed to aquaporin-4 immunoglobulin G in neuromyelitis optica spectrum disorder." (PMID 29670575, 2018). "NMOSD (also known as Devic’s disease) is a relapsing disease with the typical triad of optic neuritis, myelitis, and positive NMO-IgG, an autoantibody to the protein channel aquaporin-4 (AQP4), which is expressed on foot processes of astrocytes." (PMID 29949034, 2018).
neuromyelitis optica spectrum disorder (continued). "In view of MRI, cord spinal T2 lesions non-suggestive of MS, and tests for anti-aquaporin 4(AQP4) antibodies in serum and CSF were weakly positive, we diagnosed her neuromyelitis optica spectrum disorder(NMOSD)." (PMID 28056870, 2017). "Antibodies to myelin oligodendrocyte glycoprotein (MOG-IgG) have been described in patients with neuromyelitis optica spectrum disorders (NMOSD) without aquaporin-4 antibodies (AQP4-IgG)." (PMID 28840314, 2017). "Neuromyelitis optica spectrum disorders (NMOSD) are demyelinating autoimmune diseases in the central nervous system (CNS) that are characterized by a high relapse rate and the presence of anti-aquaporin 4 antibodies (AQP4-IgG) in the serum." (PMID 28679367, 2017). "Neuromyelitis optica spectrum disorders (herein called NMO) is an inflammatory demyelinating disease of the central nervous system in which pathogenesis involves complement-dependent cytotoxicity (CDC) produced by immunoglobulin G autoantibodies targeting aquaporin-4 (AQP4-IgG) on astrocytes." (PMID 28212662, 2017). "MOG-IgG was absent in 221 further controls, including 83 patients with AQP4-IgG-seropositive neuromyelitis optica spectrum disorders and 85 with multiple sclerosis (MS)." (PMID 27788675, 2016). "Antibodies against myelin oligodendrocyte glycoprotein (MOG-IgG) have been reported in patients with aquaporin-4 antibody (AQP4-IgG)-negative neuromyelitis optica spectrum disorders (NMOSD)." (PMID 27802824, 2016). "Anti-AQP4 antibody and oligoclonal bands, which are specific for neuromyelitis optica (NMO) and multiple sclerosis, respectively were negative in our patient." (PMID 26361577, 2015). "By analogy, aquaporin-4 antibodies were not readily detected in the CSF in neuromyelitis optica patients." (PMID 24817862, 2014). "Most neuromyelitis optica (NMO) patients have IgG against aquaporin-4 (AQP4), here termed AQP4-IgG." (PMID 24685353, 2014). "Even though the first data regarding neuromyelitis optica date back to the 19th century, it was not until 2004 that the discovery of AQP4 antibodies led to a better understanding of the pathology, thereby making the differential diagnosis of multiple sclerosis more feasible." (PMID 40362691, 2025). "Testing neuromyelitis optica (NMO) with AQP4 antibodies was negative." (PMID 41346451, 2025). "Neuromyelitis optica spectrum disorder (NMOSD) includes conditions with autoimmune genesis, which are manifested by attacks of optic neuritis (ON) and transverse myelitis (TM), and also express aquaporin 4 (NMO-IgG) or myelin oligo-endocytic glycoprotein (MOGAb) antibodies." (PMID 39781148, 2024). "Additionally, ancillary testing including brain magnetic resonance imaging (MRI), spinal MRI, cerebrospinal fluid studies, and AQP4 and MOG antibody tests may be performed to rule-out multiple sclerosis for neuromyelitis optica in cases with ON24,25." (PMID 38429319, 2024). "As a result, MOG antibodies have been found in patients with optic neuritis, acute myelitis, neuromyelitis optica spectrum disorders (NMOSD) without aquaporin 4 (AQP4) antibodies, acute disseminated encephalomyelitis (ADEM), and brainstem and cerebral cortical encephalitis." (PMID 37545724, 2023). "Given this, the role of AQP4-IgG in the pathology of Neuromyelitis Optica Spectrum Disorders may lie elsewhere, possibly in initiating immunological cascades that lead to tissue damage rather than directly affecting water transport through AQP4." (PMID 37762642, 2023). "Neuromyelitis optica spectrum disorder (NMOSD) is a central nervous system autoimmune disease that preferentially targets the optic nerves and spinal cord and has a clear female preponderance, with female to male ratios ranging from 3:1 to 9:1 in aquaporin 4 antibody (AQP4-ab) seropositive patients." (PMID 35331161, 2022).
neuromyelitis optica spectrum disorder (continued). "Neuromyelitis optica spectrum disorders (NMOSD) are autoimmune diseases of thecentral nervous system (CNS) that mainly affect the optic nerve and the spinal cord.In the majority of cases, the pathology depends on the damage of astrocytes mediatedby an auto-antibody to aquaporin-4 (AQP-4)." (PMID 34259579, 2022). "Some have speculated that C57B/6 EAE may actually be a better model for neuromyelitis optica (NMO), a rare autoimmune neurodegenerative disease very similar in phenotype to MS in which antibodies to aquaporin 4 and neutrophils are known to contribute to the formation of demyelinating lesions." (PMID 35651353, 2022). "Moreover, the interest in OAP studies has recently increased since the discovery of their involvement in the pathogenesis of Neuromyelitis Optica (NMO), a CNS autoimmune channelopathy whose autoantibodies are only able to attack their antigen AQP4 if arranged in OAPs54–56." (PMID 34934080, 2021). "During the prospective follow-up, 66 participants met McDonald 2010 diagnostic criteria for MS, while 11 were diagnosed as having a relapsing non-MS disease, 1 as having AQP4-positive neuromyelitis optica spectrum disorder, and 196 as having a monophasic course." (PMID 31545352, 2020). "Anti-aquaporin 4 antibodies (Neuromyelitis optica-Immunoglobulin G - NMO IgG) testing was negative." (PMID 32600459, 2020). "For instance, neuromyelitis optica (NMO) targets the optic nerve and spinal cord resulting in their degeneration and this is largely thought to be due to the production of auto-Abs targeting aquaporin 4 (AQP4), which is highly expressed in the central nervous system (CNS)." (PMID 31824518, 2019). "Serum samples from 64 patients with neuromyelitis optica spectrum disorders (NMOSD) (including NMO, longitudinally extensive myelitis-LETM, optical neuritis and myelitis) and 27 controls were tested for anti-AQP4 antibodies." (PMID 32257061, 2019). "Myasthenia gravis (MG) and neuromyelitis optica (NMO) are autoimmune channelopathies of the peripheral neuromuscular junction (NMJ) and central nervous system (CNS) that are mainly mediated by humoral immunity against the acetylcholine receptor (AChR) and aquaporin-4 (AQP4), respectively." (PMID 29312313, 2017). "Finally, AIs are regularly negative also in AQP4-IgG-positive neuromyelitis optica spectrum disorders (NMOSD) and in MOG-IgG-positive encephalomyelitis, two diseases in which a direct pathogenic impact of the antibody has been proven or is﻿ highly likely." (PMID 27776522, 2016). "Devic's syndrome, nowadays known as neuromyelitis optica (NMO), is considered a distinct disorder from MS, since it recognizes a different inflammatory pathway and the presence of aquaporin-4 (anti-NMO) antibodies is considered the main pathogenetic player and a diagnostic biomarker." (PMID 25374937, 2014). "The absence of anti-AQP4 antibody argued against neuromyelitis optica spectrum disorder." (PMID 24373538, 2013). "In addition, AQP-4 is present in the kidney and gastrointestinal tract, but involvement of these regions has not been described in neuromyelitis optica so far and AQP-4 does not explain the distribution of NMO lesions." (PMID 22379456, 2011). "Neuromyelitis optica spectrum disorders were excluded with negative anti-aquaporin-4 (NMO-IgG) and anti-myelin oligodendrocyte glycoprotein (MOG) antibodies." (PMID 40959376, 2025). "The role that anti‐MOG antibodies might be playing in this disease model is intriguing due to their association with other neurological conditions such as pediatric MS, neuromyelitis optica in AQP‐4 antibody‐negative cases and occasionally anti‐NMDA‐receptor encephalitis." (PMID 30578556, 2019). "Given the pathological heterogeneity between AQP4-IgG positive and negative neuromyelitis optica spectrum disorder (NMOSD), only AQP4-IgG–positive patients were enrolled to ensure cohort homogeneity." (PMID 40735294, 2025).
neuromyelitis optica spectrum disorder (continued). "At disease onset, MOG-IgG was positive by a fixed CBA, while AQP4-IgG and OCB of CSF were negative, thereby excluding neuromyelitis optica spectrum disorder and multiple sclerosis." (PMID 41459522, 2025). "The absence of brain lesions on the MRI supported the exclusion of multiple sclerosis (MS), while the lack of oligoclonal bands in the CSF and negative anti-AQP4 and anti-MOG antibody results argued against neuromyelitis optica spectrum disorder (NMOSD)." (PMID 41002717, 2025). "Antineutrophil cytoplasmic antibodies (ANCA) testing for vasculitis was negative, as well as AQP4 and MOG antibodies for the workup of neuromyelitis optica (NMO)." (PMID 39650894, 2024). "Serological testing for the anti-nuclear antibody, anti-phospholipid antibodies, neuromyelitis optica, anti-NMDA, AQP-4, and MOG antibodies was also negative." (PMID 33726699, 2021). "The new nomenclature defines the unifying term neuromyelitis optica spectrum disorders (NMOSD), which is stratified further by serologic testing (NMOSD with or without AQP4-IgG)." (PMID 30696485, 2019). "OAP is the target of anti-AQP4 antibodies in neuromyelitis optica spectrum disorder (NMOSD), in which antibodies target specifically the OAP rather than monomeric M1 AQP4 (see further discussion below)." (PMID 30691235, 2019). "In addition, RGMa may also be involved in neuromyelitis optica (NMO) as in an NMO animal model similar effects of anti-RGMa treatment were observed such as a more favourable disease course, a weaker immune response, and a partial restoration of AQP4 and GFAP reactivity." (PMID 33324887, 2019). "Anti-aquaporin 4 (AQP4) and anti-myelin oligodendrocyte glycoprotein (MOG) antibodies were accomplished in order to rule out neuromyelitis optica (NMO) and both tests were negative." (PMID 31656191, 2019). "Currently, most researchers in the field believe that although MOG-ON is similar to AQP4-ON in clinical manifestations, unlike AQP4-ON, MOG-ON is not an immune subtype of neuromyelitis optica spectrum disorder (NMOSD), but a subtype of MOG antibody-related diseases (MOGAD)." (PMID 36969199, 2023). "Hence, some dual negative test results for AQP4-Ab and MOG-Ab may be false-negative since previous investigations revealed that AQP4-Ab can be detected positive in CSF samples of some AQP4-Ab-seronegative neuromyelitis optica patients." (PMID 38054007, 2023).